NEDD4 (NEDD4 E3 ubiquitin protein ligase)
Diseases named in the same sentence as NEDD4 in open-access papers (continued):
Sharing a sentence is not in itself a finding about the gene and the disease.
cancer (continued). "Hence, our findings revealed the CKI/SCFβ-TRCP signaling axis as the upstream negative regulator of NEDD4, and further suggested that enhancing NEDD4 degradation, presumably with CKI or SCFβ-TRCP agonists, could be a promising strategy for treating human cancers." (PMID 24657926, 2014). "Hence, inactivation of SAG either by siRNA silencing of itself, or by overexpression of its upstream E3 ligase, NEDD4-1 (this study), or by its small molecule inhibitor, MLN4924, all induces apoptosis, further supporting the notion that SAG E3 ligase is an attractive anti-cancer target." (PMID 25216516, 2014). "According to the negative correlation between NEDD4 and HER3, NEDD4 can be a potential target for HER3-positive cancer treatment." (PMID 38835349, 2024). "Although the mechanisms by which the novel SS18::NEDD4 gene fusion have not been fully elucidated, individual perturbations in SS18‐ and NEDD4‐mediated signaling pathways are recognized for promoting human cancer and tumorigenesis." (PMID 35639915, 2022). "Cell culture experiments and human cancer tissue suggested that PTEN might be a NEDD4-1 and NEDD4-2 substrate), but analysis of NEDD4-1 and NEDD4-2 knockout mice has shown that PTEN stability, subcellular localisation, and activity are not altered in the absence of NEDD4-1 and/or NEDD4-2." (PMID 35328067, 2022).
tumor (79 papers, 2013 to 2025). "Taken together, these results indicate that loss of NEDD4 reduces tumour growth and altered response to 5-FU." (PMID 38097550, 2023). "Even though the loss of NEDD4 exhibited resistance to 5-FU, a significant reduction in tumour size was also observed upon loss of NEDD4." (PMID 38097550, 2023). "E3 ligase neuronal precursor cell-expressed developmentally downregulated 4 (NEDD4) is responsible for the proteasomal degradation of p21, a key negative regulator of tumor proliferation that associates with G1 arrest." (PMID 38104139, 2023). "In GCA, NEDD4 is overexpressed, and this is linked to tumor invasion and metastasis, as well as survival rate in rats." (PMID 36293239, 2022). "NEDD4 is probably involved in the signaling that leads to tumor metastasis caused by the EGFR because NEDD4 facilitates EGF-dependent GC cell invasion and migration." (PMID 36293239, 2022). "The data imply that upregulation of Rspo‐Lgr5 signalling upon Nedd4/Nedd4l loss increases tumour predisposition and progression in Apcmin animals by promoting Wnt activation and ISC self‐renewal." (PMID 31867777, 2020). "In this study, we observed that hsa-miR199a-3p caused the downregulation of NEDD4 in NB cells and consequently promoted tumor proliferation and migration." (PMID 31249805, 2019). "High NEDD4-expressing BC was associated with a large tumor size (χ2 = 8.973, P = 0.030) and a high incidence of lymph node invasion (χ2 = 10.111, P = 0.001)." (PMID 31856858, 2019). "In order to determine if NEDD4 expression is associated with BC progression, we subgrouped BC samples based on tumor progression and advantage." (PMID 31856858, 2019). "We found that knockdown of NEDD4 or H3 K23/36/37R mutation reduced the tumour incidence and average tumour size, suggesting that NEDD4-mediated H3 ubiquitination is also required for the tumorigenecity of Aldh+ cells in vivo." (PMID 28300060, 2017). "Finally, our study demonstrated that NEDD4 induced the degradation of HBx in an ubiquitin-proteasome-dependent manner via K48-linked ubiquitination, which suppressed tumor progression in HBV-positive HCC." (PMID 33767993, 2021). "Of note, loss of Nedd4l appears to be more effective in tumour progression than Nedd4 ablation." (PMID 31867777, 2020). "Next, we asked if the tumour‐promoting role of Nedd4 and Nedd4l was associated with Wnt signalling." (PMID 31867777, 2020). "In addition, NEDD4 expression was associated with tumor size, TNM stage, nodal status, and ER and PR status." (PMID 31856858, 2019). "In addition, NEDD4-positive staining was associated with clinical parameters, including tumor size (P = 0.030), nodal status (P = 0.001), estrogen receptor status (P = 0.035), and progesterone receptor status (P = 0.023)." (PMID 31856858, 2019). "Notably, we found that in vitro tumour sphere numbers and Aldh+ cell population were reduced upon glucose depletion, NEDD4 knockdown, NEDD4 tyrosine phosphorylation-deficient mutation, GCN5 knockdown, H3.3 knockdown and deficiency of H3 ubiquitination." (PMID 28300060, 2017). "Likewise, NEDD4 has been implicated in regulation of insulin-like growth factor signaling, T-cell-mediated immunity, and tumor suppression." (PMID 26263374, 2015). "Finally, the tumor suppressor role of NEDD4 in HBV-associated HCC was observed in vivo." (PMID 33767993, 2021). "Mechanistically, NEDD4-1 mediates tumor-suppressive effects through targeting pAkt-Ser473 for ubiquitination degradation, and suppressing PTEN/PI3K/Akt pathway." (PMID 40809696, 2025). "As a plasma membrane‐anchoring E3 ligase that contains WW domains predictably recognizing PPXY motifs, NEDD4 was reported to have tumour suppressive roles through targeting Ras proteins or degradation." (PMID 39843398, 2025). "To date, numerous studies have reported the involvement of NEDD4 in the regulation of tumor proliferation, metastasis, and stemness." (PMID 39890782, 2025).
tumor (continued). "NEDD4 has previously been reported to ubiquitylate H3 on multiple lysine residues (K23, K36, K37) in tumour cells, easing the transcriptional re‐activation of genes through the establishment of the H3K9Ac mark." (PMID 40911795, 2025). "The up-regulated genes including NEDD4, NEDD4 E3 ubiquitin protein ligase, play critical roles in the regulation of a number of membrane receptors, endocytic machinery components and the tumor suppressor PTEN." (PMID 39707500, 2024). "The results depicted that the tumor volume and weight were reduced in the lenti-sh-NEDD4 group compared to the lenti-vector group." (PMID 39444619, 2024). "When A549CSC cells were transfected with lenti-FLRT2, tumor volume, and weight were significantly reduced, whereas NEDD4 overexpression blocked the inhibitory effects of lenti-FLRT2 on tumor growth." (PMID 39444619, 2024). "The findings of this study indicated that NEDD4 has the potential to significantly influence tumor treatment resistance." (PMID 37605223, 2023). "Human ortholog, GUCD1 (LLN4), interacts with NEDD4-1 affecting tumor suppressors and lacks the domain providing the cyclase function described for GC1." (PMID 37164157, 2023). "NEDD4 mRNA levels were also higher than expected in PDAC tumor samples from patients of our hospital." (PMID 37605223, 2023). "Consistent with in vitro data of cell proliferation and colony formation, NEDD4 KO cells exhibited significantly smaller tumours 17 days post injection." (PMID 38097550, 2023). "NEDD4 also promotes ubiquitination and degradation of Beclin 1, a tumor-suppressive protein and a central autophagy mediator." (PMID 37176148, 2023). "Taken together, these data suggest that NEDD4 regulates cell proliferation, colony formation, tumour growth and chemoresistance to 5-FU in CRC cells." (PMID 38097550, 2023). "And the role of NEDD4 has been expanded to tumor biology since it was reported to be an E3 ubiquitin ligase of PTEN." (PMID 36774408, 2023). "Both in vitro and in vivo experiments indicate that Dox-induced knockdown of NEDD4 significantly suppresses tumor growth of IGF1R-dependent GC cells and NEDD4 overexpression promotes tumor growth of IGF1R-dependent GC cells." (PMID 36774408, 2023). "The rescue experiments show that a PTEN-IRS1 axis is required for NEDD4-mediated regulation of Akt activation and tumor growth in GC cells." (PMID 36774408, 2023). "And the pre-requirement for the tumor suppressive effect of NEDD4 inhibition is the existence of PTEN in GC cells." (PMID 36774408, 2023). "But the most important finding in our study is that the NEDD4 targeted strategy can only efficiently inhibit tumor growth in the IGF1 signaling-driven GC." (PMID 36774408, 2023). "The average size of NEDD4 KO mouse xenografts tumour was < 50 mm3 whereas WT xenograft tumour grew up to 250 mm3." (PMID 38097550, 2023). "Considering that loss of PTEN results in lower insulin resistance and lipogenesis, which is responsible for tumor microenvironment establishment, NEDD4 reprograms metabolic status and tumor progression through PTEN ubiquitination." (PMID 37176148, 2023). "Next, we sought to determine if NEDD4 KO cells can regulate tumour growth and chemoresistance in vivo." (PMID 38097550, 2023). "Overall, PTEN has a significant role in tumor suppression, but the NEDD4-1-mediated targeting of PTEN resulted in carcinogenesis." (PMID 37568787, 2023). "On the other hand, phosphatase and tensin homology deleted on chromosome 10 (PTEN) is a tumor suppressor and a polyubiquitination target of Nedd4, and Nedd4-mediated PTEN ubiquitination results in PTEN proteasomal degradation." (PMID 37023120, 2023). "Overall, we show that NEDD4 regulates cell proliferation, colony formation, tumour growth and 5-FU chemoresistance in CRC cells." (PMID 38097550, 2023). "Apart from the oncogenic property of NEDD4 revealed in several studies, some reports state the tumor-suppressing role of NEDD4 in BC." (PMID 36293239, 2022).
tumor (continued). "In vivo findings verified that NEDD4 regulated the KLF8/miR-132/NRF2 axis by accelerating tumor growth and lung metastasis." (PMID 35031788, 2022). "Tumor volume and weight were markedly elevated in the presence of NEDD4 but were diminished when sh-NRF2 was used to knock down NRF2 expression." (PMID 35031788, 2022). "Hangyu Li at the China Medical University in Shenyang, China, and co-workers examined NEDD4 activity in experiments on human tumor cell cultures and mice." (PMID 35031788, 2022). "A surfeit of studies suggests that the NEDD4 protein has both oncogenic and tumor-suppressive properties." (PMID 36293239, 2022). "For example, a study has demonstrated the tumor-suppressing role of NEDD4 by which PIP5Kα, a ubiquitinated protein that enhances the proliferation, invasion, and migration of BC cells, was impeded by NEDD4." (PMID 36293239, 2022). "In our study, we identified a new canonical mechanism of RORα-mediated tumour suppression by which the transcription of the ubiquitinase NEDD4 is activated, leading to c-myc degradation." (PMID 36316442, 2022). "In conclusion, our investigation clarified that NEDD4L exerts tumor-suppressive activity in MM, similar to its homolog NEDD4-1." (PMID 35236820, 2022). "As NEDD4-1 negatively regulates PTEN, the deletion of NEDD4-1 inhibits tumor growth in a PTEN-dependent manner." (PMID 35954330, 2022). "In summary, our study first demonstrated that NEDD4 expression was irrelevant to HBV exposure in HCC tumor tissue but that high NEDD4 expression was related to a better OS and PFS than low expression in patients with HBV-associated HCC." (PMID 33767993, 2021). "Consistently, our in-house SHH-GBM patient cohort tumor IHC staining showed an increased expression level of NEDD4-1 in the GBM tissue compared with normal tissue." (PMID 34638586, 2021). "NEDD4-1 has several upstream and downstream genes, and, with its perceived dual role in cancer, it can be used as a molecular switch to control tumor growth through its competitive substrates." (PMID 34638586, 2021). "On the other hand, NEDD4 inhibits tumor proliferation by binding to MYC, inhibiting HER3 expression, and targeting PIP5K1A." (PMID 34458018, 2021). "On the one hand, NEDD4 promotes tumor survival by inducing cell proliferation, inhibiting apoptosis, disrupting the cell cycle, promoting cell migration and invasion, and enhancing drug resistance." (PMID 34458018, 2021). "Our findings suggest that NEDD4 exerts a tumor-suppressive effect in HBV-associated HCC by acting as an E3 ubiquitin ligase for HBx degradation and provide new insights into the function of NEDD4." (PMID 33767993, 2021). "NEDD4 is frequently overexpressed in many different human malignancies and can act as either an oncogene or a tumor suppressor." (PMID 33767993, 2021). "We noticed that NEDD4 overexpression sharply decreased tumor size compared to that in the control group." (PMID 33767993, 2021). "Inactivation of NEDD4 and NEDD4L increases Wnt activation and ISC numbers, which subsequently enhances tumour predisposition and progression." (PMID 31867777, 2020). "A number of studies have shown that NEDD4 is an oncoprotein that catalyzes the ubiquitination and the degradation of target proteins that are commonly known as tumor suppressors, such as PTEN and LATS." (PMID 33014839, 2020). "The staining of 4HNE was significantly increased after erastin treatment in both control cells and Nedd4 depletion cells, suggesting that erastin increased the lipid peroxidation level of tumor xenograft samples." (PMID 31974380, 2020). "NEDD4 overexpression and downregulation were employed to validate the critical role of NEDD4 in the NC-mediated tumor suppressive effects." (PMID 33288736, 2020). "NEDD4 (neuronally expressed developmentally downregulated 4) has been characterized as an oncoprotein in carcinogenesis and tumor progression." (PMID 33288736, 2020).
tumor (continued). "Our data demonstrate that both Nedd4 and Nedd4l exacerbate Apcmin tumour phenotype, indicating that they are both tumour suppressors." (PMID 31867777, 2020). "The inhibition of NEDD4‐1 expression promoted tumor growth, and NEDD4‐1 OE exerted an antitumor effect in vivo." (PMID 31390487, 2020). "NEDD4-1 acts as an oncogene as well as a tumor suppressor in cancers, and NEDD4-1 activators or inhibitors are urgently needed." (PMID 31787758, 2019). "In fact, NEDD4-1 exhibits a dual role and acts as either an oncogene or tumor suppressor, which depends heavily on the context." (PMID 31787758, 2019). "Low NEDD4-1 levels enhance HER3-mediated tumor growth in vivo and cell proliferation and migration in vitro." (PMID 31787758, 2019). "In conclusion, this study reveals that exosomal hsa-miR199a-3p can promote tumor proliferation and migration via decreasing NEDD4 expression in NB patients and cells." (PMID 31249805, 2019). "We found that NEDD4 is required for the proliferation of BC, which supports the observation that NEDD4 expression was elevated in human BC tumor tissue compared to normal BC tissue." (PMID 31856858, 2019). "NEDD4 functions as an oncogene by facilitating the activation of Akt, a protein related to tumor development, drug resistance, and poor prognosis." (PMID 31856858, 2019). "NEDD4 immunoreactivity, patient’s age, tumor size, histological grade, and nodal status were chosen as risk variables since all are potential factors affecting a poor prognosis for BC." (PMID 31856858, 2019). "Of all 445 samples, 63.8% of tumor samples were positive for NEDD4 staining, which is similar to a previous report in which NEDD4-positive expression was observed in 55% of BC tumor samples." (PMID 31856858, 2019). "Next, NEDD4 protein expression was compared with several clinicopathologic variables in BC, such as age, menstruation status, tumor size, histological grade, lymph node involvement, and molecular subtypes." (PMID 31856858, 2019). "Our studies have shown that NEDD4 overexpressed in gastric cardia adenocarcinoma (GCA), and its overexpression is correlated with the tumor invasion and metastasis, and inversely associated with the survival rate." (PMID 29455656, 2018). "The 5-year survival rate in NEDD4-negative GCA patients is as high as 96%, suggesting that NEDD4 is an oncogenic protein that plays a key role in GCA tumor progression and metastasis." (PMID 29455656, 2018). "We studied correlations between HER3, NEDD4–1, and NRDP1 protein expression and their association with tumour histopathological characteristics and clinical outcomes." (PMID 30367623, 2018). "Remarkably, co-administration of NAC and IL1β completely rescued the defect in tumour sphere formation upon NEDD4 knockdown, suggesting both IL1β and anti-oxidant are critical for tumour sphere formation." (PMID 28300060, 2017). "Treatment of N-acetyl-L-cysteine (NAC), a widely used ROS scavenger, not only increased tumour sphere number in control cells but also partially rescued NEDD4 knockdown phenotype." (PMID 28300060, 2017). "PTEN, one of the major tumor suppressors, was recently shown to be ubiquitylated and degraded by NEDD4." (PMID 25823820, 2015). "In contrast, NEDD4L mRNA, the closest homolog to NEDD4, was the most highly downregulated family member, and was significantly downregulated in all tumor stages." (PMID 24312311, 2013). "Given that NEDD4 expression is regulated by H3K14la, we determined whether the tumor suppression induced by oxamate could be rescued by increasing NEDD4." (PMID 39890782, 2025). "Overall, our study found that the tumor suppressive effects of blocking histone lactylation could be hindered by OE-NEDD4, indicating that the tumor promotion effect mediated by histone lactylation was partly achieved through NEDD4." (PMID 39890782, 2025). "However, NEDD4-1 depicts the tumor suppressive and anti-autophagic roles in melanoma cancer cells where it negatively regulates autophagy via destabilizing IGPR-1." (PMID 36918822, 2023).